LINC02754 (long independently transcribed non-coding RNA 2754)
Gene: Long non-coding RNA gene on chromosome 11 (67,840,851 to 67,906,350, forward strand). Ensembl gene ENSG00000251637.
Gene Ontology:
Biological process: miRNA-mediated post-transcriptional gene silencing